KANK2 (KN motif and ankyrin repeat domains 2)
Description:
Involved in transcription regulation by sequestering in the cytoplasm nuclear receptor coactivators such as NCOA1, NCOA2 and NCOA3. Involved in regulation of caspase-independent apoptosis by sequestering the proapoptotic factor AIFM1 in mitochondria. Pro-apoptotic stimuli can induce its proteasomal degradation allowing the translocation of AIFM1 to the nucleus to induce apoptosis. Involved in the negative control of vitamin D receptor signaling pathway. Involved in actin stress fibers formation through its interaction with ARHGDIA and the regulation of the Rho signaling pathway. May thereby play a role in cell adhesion and migration, regulating for instance podocytes migration during development of the kidney. Through the Rho signaling pathway may also regulate cell proliferation (By similarity).
Synonyms: SIP; ANKRD25; KIAA1518; MXRA3; NPHS16; PPKWH
Tractability: PROTAC: ubiquitination databases record sites on it; its protein half-life has been measured.
Gene: Protein-coding gene on chromosome 19 (11,164,267 to 11,197,945, reverse strand). Ensembl gene ENSG00000197256.
Subcellular location: Cytoplasm; Mitochondrion
Subcellular location (Human Protein Atlas): Nucleoplasm; Cytosol
Gene Ontology:
Molecular function: protein binding
Biological process: kidney epithelium development; negative regulation of cell population proliferation; negative regulation of G1/S transition of mitotic cell cycle; negative regulation of intracellular estrogen receptor signaling pathway; negative regulation of programmed cell death; negative regulation of transcription by RNA polymerase II; negative regulation of vitamin D receptor signaling pathway; podocyte cell migration; regulation of Rho protein signal transduction; establishment or maintenance of cell polarity; negative regulation of actin filament polymerization
Cellular component: cytoplasm; cytosol; mitochondrion; cell cortex; microtubule associated complex
Genetic constraint (gnomAD): Loss-of-function variants: 40 observed, 73.99 expected, observed/expected ratio (o/e) 0.54, 90% interval 0.42 to 0.7. The upper end of that interval is the gene's LOEUF score, 0.7, which puts it in group 2 of 6, group 1 being the genes least tolerant of losing a copy. Missense variants: 1,144 observed, 1,203.2 expected, observed/expected ratio (o/e) 0.95, 90% interval 0.9 to 1. Synonymous variants: 537 observed, 523.61 expected, observed/expected ratio (o/e) 1.03, 90% interval 0.95 to 1.1.
Homologues: Orthologues: chimpanzee KANK2 (99% identical), macaque KANK2 (97% identical), dog KANK2 (90% identical), pig KANK2 (90% identical), guinea pig KANK2 (85% identical), rat Kank2 (83% identical), mouse Kank2 (83% identical), tropical clawed frog kank2 (50% identical), zebrafish kank2 (47% identical), Drosophila melanogaster Kank (26% identical), Caenorhabditis elegans vab-19 (23% identical). Paralogues in human: KANK1 (37% identical), KANK3 (28% identical), KANK4 (28% identical).
Diseases named in the same sentence as KANK2 in open-access papers:
KANK2 is named in the same sentence as 40 diseases in open-access papers, as found by Europe PMC text mining. Sharing a sentence is not in itself a finding about the gene and the disease. The quoted sentences say what the papers report.
nephrotic syndrome (5 papers, 2015 to 2024). A collection of symptoms that include severe edema, proteinuria, and hypoalbuminemia; it is indicative of renal dysfunction. "Given the results presented in our study and those published in the literature, individuals with nephrotic syndrome may have pathogenic variants in KIF21A, encoding a direct interaction partner of KANK1 and KANK2." (PMID 37932480, 2023). "Similarly, mutations in KN motif and ankyrin repeat domains 1/2/4 (KANK1, KANK2, and KANK4) have all been reported to be associated with nephrotic syndrome due to their interactions with proteins that interact with RhoA (KANK 1 interacts with synaptopodin and KANK2 interacts with ARHGDIA)." (PMID 32708597, 2020).
melanoma (3 papers, 2020 to 2025). A malignant, usually aggressive tumor composed of atypical, neoplastic melanocytes. "In our expanded analysis of KANK2, we evaluated its role in immune infiltration in melanoma and HCC." (PMID 39895803, 2025). "KANK2 mutations were most commonly observed in UCEC, STAD, melanoma, COAD, READ, and HNSC." (PMID 39895803, 2025). "Therefore, KANK2 is crucial for the functional connection of integrin αVβ5-containing FAs with MTs and represents a potential target for improvement of melanoma therapy." (PMID 32195252, 2020). "Therefore, we propose KANK2 as a potential target for increasing sensitivity of melanoma cells to MT poisons and decreasing migration." (PMID 32195252, 2020). "Using the TIMER and TISIDB databases, we found that KANK2 expression is significantly correlated with various immune cells, including CD8+ T cells and macrophages in melanoma." (PMID 39895803, 2025). "In melanoma, liprin β1 was found to be overexpressed and its expression strongly correlated with the expression of KANK1 and KANK2." (PMID 32195252, 2020).
Nephropathy (3 papers, 2017 to 2024). A nonspecific term referring to disease or damage of the kidneys. "Eight heterozygous variants were identified in nephropathy-associated genes (CLCN2, C5orf42, GSN, LMX1B, CEP164, PKD1, ITGB4, and KANK2), but each could be discounted having been inherited from an unaffected parent." (PMID 37148394, 2023).
Obesity (2 papers, 2019 to 2025). Accumulation of substantial excess body fat. "Several of the identified loci have been implicated in ASCVD risk factors such as circulating lipids (LPA-PLG, APOE, TRIB1, KANK2), diabetes (CDKN2B-AS1, IGF2BP1) and obesity (LEPR, IGF2BP1)." (PMID 40164586, 2025).
Sepsis (2 papers, 2022 to 2024). Sepsis is defined as life-threatening organ dysfunction caused by a dysregulated host response to infection. "HSP70 plays an important role in protection of acute lung injury caused by sepsis through interaction with KANK2 to reduce AIF release and apoptotic cell." (PMID 35327602, 2022). "Previous studies have shown that HSP70 can play a protective role in ALI in sepsis by interacting with KANK2 to reduce the release of apoptosis-inducing factor and apoptosis." (PMID 38698431, 2024). "Additionally, knockdown of KANK2 in epithelial cells and deletion of hsp70.1 gene in CLP mice aggravated apoptosis and tissue damage, suggesting that interaction of KANK2 and HSP70 is critical for protecting lung injury induced by sepsis." (PMID 35327602, 2022). "Although the roles of KANK2 have been extensively described, the interaction with HSP70 to protect lung injury from sepsis has not been reported." (PMID 35327602, 2022).
acute pancreatitis (1 paper, 2022). An acute inflammatory process that leads to necrosis of the pancreatic parenchyma. "Meanwhile, KANK2 can suppress myocardial injury caused by acute pancreatitis through inhibiting the inflammatory response by deactivating p65." (PMID 35327602, 2022).
alcoholic liver diseases (1 paper, 2025). A disorder caused by damage to the liver parenchyma due to alcohol consumption. "KANK2 was principally participated in the Alcoholic liver disease, Protein digestion and absorption, NF-kappa B signaling pathway, TNF signaling pathway." (PMID 41299613, 2025).
breast carcinoma (1 paper, 2025). "In contrast, KANK2 exhibited negative correlations with inflammation, quiescence, differentiation, metastasis, and invasion in breast cancer (BRCA), as well as with angiogenesis in renal cell carcinoma (RCC) and invasion in ovarian carcinoma (OV)." (PMID 39895803, 2025).
colorectal cancer (1 paper, 2025). A primary or metastatic malignant neoplasm that affects the colon or rectum. "Further assessment revealed that KANK2 positively correlated with differentiation, quiescence, EMT, apoptosis, invasion, angiogenesis, and inflammation in colorectal cancer (CRC)." (PMID 39895803, 2025). "For instance, in cancers such as lung adenocarcinoma (LUAD) and colorectal cancer (CRC), KANK2 showed moderate AUC values, suggesting its utility in broader cancer diagnostics." (PMID 39895803, 2025).
multiple pterygium syndrome (1 paper, 2015). "Of these four variants, 2 were discarded since within genes already reported to be responsible for phenotypically divergent recessive diseases: KANK2, implicated in palmoplantar keratoderma and woolly hair (MIM 616099) and CHRNG, implicated in multiple pterygium syndrome (MIM 253290)." (PMID 25870235, 2015).
myocardial infarction (1 paper, 2022). Gross necrosis of the myocardium, as a result of interruption of the blood supply to the area, as in coronary thrombosis. "A cardioprotective effect of KANK2 against myocardial infarction through decreasing collagen deposition and apoptosis has been reported." (PMID 36419485, 2022).
Sleep apnea (1 paper, 2017). An intermittent cessation of airflow at the mouth and nose during sleep is known as sleep apnea. "Suggestive associations of symptoms of sleep apnea were observed with 11 rare variants (located in KANK2, LCN6, TRAF3, PLEK, HIF1A, SLC45A3, ERCC1/CD3EAP, MRGPRE, GRAMD4, TYW5, CST5)." (PMID 29093733, 2017).
tauopathy (1 paper, 2023). Neurodegenerative disorders involving deposition of abnormal tau protein isoforms (tau proteins) in neurons and glial cells in the brain. "The emergence of two microtubule-associated membrane scaffold proteins, STOM and KANK2, as top prioritized potential therapeutic targets for PSP, a primary tauopathy characterized by microtubule-associated protein tau neuropathology, is noteworthy." (PMID 37919278, 2023).
tumor (5 papers, 2021 to 2025). "Based on ROC and KM curve analyses, we explored the correlation between KANK2 expression and the pathological stage, T stage, and N stage in 33 tumor types, with KIRC showing the strongest association." (PMID 39895803, 2025). "Molecular docking revealed strong binding interactions between KANK2 and these compounds, involving different mechanisms such as cell cycle control, DNA synthesis, and signaling pathways that inhibit tumor cell growth and proliferation." (PMID 39895803, 2025). "Among 69 tumor types, shallow deletions, diploid states, and amplifications were common in KANK2 mRNA expression." (PMID 39895803, 2025). "Both WB and qPCR results showed that KANK2 mRNA and protein levels were significantly increased in tumor cell lines compared with normal cells (P < 0.05)." (PMID 39895803, 2025). "Overall, these findings indicate that KANK2 may impact tumor biology across various cancers by modulating the immune microenvironment and holds potential as a target for immunotherapy." (PMID 39895803, 2025). "Conversely, among the four downregulated genes (KANK2, SGCA, SLC12A4, and MEIS1), higher expression correlated with better prognosis, suggesting their potential tumor-suppressive roles." (PMID 40525903, 2025). "Both the expression of USP39 and the inclusion of KANK2 exon 2 were significantly increased in tumor samples compared to non-tumor samples in this in-house HCC cohort." (PMID 37821439, 2023).
cancer (4 papers, 2022 to 2025). A tumor composed of atypical neoplastic, often pleomorphic cells that invade other tissues. "Further support comes from ROC curve analysis, which indicates high diagnostic value for KANK2, with AUC values greater than 0.75 in 13 cancer types, including BLCA, BRCA, and CESC." (PMID 39895803, 2025). "This study aimed to analyze KANK2's expression and its diagnostic and prognostic significance across 33 cancers using multiple online databases." (PMID 39895803, 2025). "The relationship between KANK2 mutations and methylation status with cancer progression underscores the importance of these alterations in regulating KANK2 expression." (PMID 39895803, 2025). "Genetic mutations affecting KANK2 expression were analyzed using the cBioPortal online tool, encompassing all TCGA Pan-Cancer Atlas studies with 13,863 samples." (PMID 39895803, 2025). "Our study revealed that KANK2 is widely expressed in various cancers and exhibits significant diagnostic value in some of them, as indicated by ROC curve analysis." (PMID 39895803, 2025). "We explored the functional role of KANK2 across various cancer types using the CancerSEA database, which examines KANK2's association with 14 distinct functional states at single-cell resolution." (PMID 39895803, 2025). "The genetic alteration analysis of KANK2 revealed a high frequency of mutations, especially missense and truncating mutations, in cancers such as UCEC, STAD, and KIRC." (PMID 39895803, 2025). "Additionally, we investigated KANK2's associations with cancer subtypes using the TISIDB database and explored genetic alterations via cBioPortal." (PMID 39895803, 2025). "In addition to PAAD and HCC, KANK2 has also demonstrated diagnostic potential across multiple other cancer types." (PMID 39895803, 2025). "These mutations may disrupt KANK2's normal function, contributing to cancer development and progression." (PMID 39895803, 2025). "This highlights the versatility of KANK2 as a biomarker, which could be valuable either independently or as part of a panel of biomarkers, improving diagnostic specificity and sensitivity across different types of cancers." (PMID 39895803, 2025). "To bridge these gaps, we conducted a comprehensive analysis of KANK2 expression across 33 cancer types, utilizing data from The Cancer Genome Atlas (TCGA) and the GTEx project." (PMID 39895803, 2025). "The results were consistent across these three cancers, demonstrating that KANK2 expression is aligned with previous findings, thereby confirming its potential significance as a biomarker." (PMID 39895803, 2025). "Validation through GEO datasets and protein-protein interaction (PPI) network construction further contextualized KANK2's role in cancer biology." (PMID 39895803, 2025). "Using the UALCAN online tool, we assessed KANK2 promoter methylation levels across various patient and normal groups for different cancer types." (PMID 39895803, 2025). "Second, the experimental validations for KANK2 were conducted primarily in specific cancer types, including KIRC, PAAD, and HCC." (PMID 39895803, 2025). "Given the impact of KANK2 expression on OS in four cancers, we analyzed its expression across immune and molecular subtypes of these and 29 other cancers." (PMID 39895803, 2025). "Survival analysis indicated that KANK2 expression is significantly associated with overall survival (OS) and disease-specific survival (DSS) in several cancers." (PMID 39895803, 2025). "Functional state analysis using CancerSEA revealed that KANK2 is significantly correlated with several cancer-related processes, such as EMT, differentiation, angiogenesis, metastasis, invasion, apoptosis, and inflammation." (PMID 39895803, 2025). "Studies have found that epithelial–mesenchymal transition (EMT) and angiogenesis are abnormal in cancers with high KANK2 expression, while ECM imbalance, excessive innervation of sensory nerves and vascularization are common phenomena in IDD." (PMID 41299613, 2025).
cancer (continued). "Addressing these limitations in future research will provide a more comprehensive understanding of KANK2's biological functions and its potential clinical applications across different cancers." (PMID 39895803, 2025). "While these experiments provided valuable insights, validations across a broader range of cancer types are necessary to further confirm KANK2's role as a pan-cancer biomarker." (PMID 39895803, 2025). "KANK2's activation pathways, primarily in cancers, included EMT, hormone AR, RASMAPK, and RTK, while inhibition pathways encompassed the cell cycle, apoptosis, and PI3K/AKT." (PMID 39895803, 2025). "A comprehensive investigation into KANK2 expression across diverse cancer types revealed notable patterns of differential expression, which may have significant diagnostic relevance." (PMID 39895803, 2025). "Prospective studies, experimental validation in diverse cancer types, and mechanistic investigations are essential to deepen our understanding of KANK2's functional roles and therapeutic potential, ultimately enhancing its translational impact as a biomarker and therapeutic target in oncology." (PMID 39895803, 2025). "However, a thorough evaluation of KANK2's expression and function across various cancer types is still missing." (PMID 39895803, 2025). "In summary, this study provides a comprehensive analysis of KANK2, elucidating its expression patterns across cancers and their clinical implications, thereby positioning KANK2 as a promising candidate for biomarker development and therapeutic intervention in oncology." (PMID 39895803, 2025). "In addition, using the TIMER2.0 database, we further analyzed the relationship between KANK2 expression and immune cell infiltration across the 33 cancers." (PMID 39895803, 2025). "Our investigation into KANK2 expression across various cancer types, along with its involvement in signaling pathways, mutation sites, promoter DNA methylation, immune infiltration, GOKEGG pathway analyses, and drug associations, has illuminated its critical role in cancer biology." (PMID 39895803, 2025). "Kaplan-Meier and Cox regression analyses demonstrated that elevated KANK2 expression correlates with improved overall survival (OS) and disease-specific survival (DSS) in cancers such as KIRC, SARC, and UVM." (PMID 39895803, 2025). "Therefore, combining KANK2 inhibition with immune checkpoint inhibitors (such as PD-1/PD-L1 blockers) may produce synergistic effects, enhancing the efficacy of immunotherapy in these cancers." (PMID 39895803, 2025). "Furthermore, the relationship between KANK2 and various cancer subtypes—both molecular and immunological—has not been extensively explored." (PMID 39895803, 2025). "Negative LASSO coefficients were found for the genes KANK2 and CLEC4D that were downregulated in cancer compared with normal samples, but their log2FC was between −1 and −2." (PMID 36552262, 2022).
neurodegenerative disease (1 paper, 2025). A disorder of the central nervous system characterized by gradual and progressive loss of neural tissue and neurologic function. "KANK2 plays an important role as a scaffold in cortical microtubule stabilization complexes, which has been manifested to serve as a promising diagnostic marker for neurodegenerative diseases by cross-species validations." (PMID 41299613, 2025).
KANK2 also shares sentences with these, for which no sentence is quoted: glioblastoma (2 papers); atherosclerosis (1); bladder cancer (1); cerebral palsy (1); cervical squamous cell carcinoma (1); cholangiocarcinoma (1); colon adenocarcinoma (1); diabetes (1); head and neck squamous cell carcinoma (1); hereditary hypotrichosis simplex (1); kidney (1); lung adenocarcinoma (1); Lung Injury (1); lung squamous cell carcinoma (1); ovarian carcinoma (1); Palmoplantar keratoderma (1); pancreatic adenocarcinoma (1); progressive supranuclear palsy (1); prostate adenocarcinoma (1); rectum adenocarcinoma (1); renal cell carcinoma (1); sarcopenia (1); thyroid carcinoma (1); uterine corpus endometrial carcinoma (1).